TIMP2 (TIMP metallopeptidase inhibitor 2)
Diseases named in the same sentence as TIMP2 in open-access papers (continued):
Sharing a sentence is not in itself a finding about the gene and the disease.
tumor (continued). "The expression of MMP-9 or TIMP-2 by tumour cells, MMP-1, 7, 9, 11, 13, or TIMP-3 by fibroblastic cells, and MMP-7, 9, 11, 13, 14, TIMP-1, or TIMP-2 by mononuclear inflammatory cells, was also significantly associated with a higher rate of distant metastases." (PMID 17342087, 2007). "Synthetic (GM6001, 20 uM) and endogenous (TIMP-2, 10 nM) broad spectrum MMP inhibitors were able to inhibit tumor cell invasion into the matrix." (PMID 16515711, 2006). "In HT1080 tumor cells, both protein and mRNA levels of TIMP1, TIMP2, MMP2 and MMP9 are increased by butyrate treatment." (PMID 16972989, 2006). "We found TIMP-1, TIMP-2 and TIMP-3 to be highly expressed both in normal tissue and in tumour tissue, with increased expression in high-grade tumours." (PMID 16465195, 2006). "In our study celecoxib was able to neutralize the inductive potential of the tumor cell microenvironment by decreasing levels of MMPs, TIMP1, TIMP2, and laminin." (PMID 17156488, 2006). "Significant correlations were found between detection of MT1-MMP and MMP-2 in tumour cell cytoplasm (P< 0.05), of MT1-MMP and TIMP-2 in tumour cell cytoplasm (P< 0.01), and of MMP-2 and TIMP-2 in tumour cell cytoplasm (P< 0.01)." (PMID 10901373, 2000). "Indeed, GO treatment resulted in the upregulation of several miRNA-21 responsive genes involved in inflammation and tumor progression including IL-8, ICAM-1, TIMP-2, and NF-κB." (PMID 41596621, 2026). "Enriched in PC3-ML cells, exosomal miR-888 downregulates important proteins such as Krüppel-like factor 5 (KLF5), retinoblastoma-like protein 1 (RBL1), tissue Inhibitor of metalloproteinases 2 (TIMP2), and SMAD family member 4 (SMAD4), enhancing overall tumor cell capabilities." (PMID 40556678, 2025). "PC3-ML cells contain high levels of exosomal miR-888, which downregulates proteins such as Krüppel-like factor 5 (KLF5), retinoblastoma-like protein 1 (RBL1), tissue Inhibitor of metalloproteinases 2 (TIMP2), and SMAD family member 4 (SMAD4), strengthening tumour cell abilities." (PMID 41465110, 2025). "It is thought that, in contrast to epithelial markers, such as plakoglobin or cytokeratins 18 and 19, mesenchymal markers, TIMP-2, TIMP-3, thrombospondin-1 and/or α1VI/α2I integrins may predict the invasive and metastatic phenotype of tumour cells." (PMID 40724562, 2025). "Both inhibitors are predicted or validated targets of T2D-enriched miRNAs (TIMP2 by miR-93-5p; LACTB by miR-374a), suggesting that luminal-like tumor cells may be key sites of miRNA-driven repression that contributes to broader MMP activation." (PMID 40858992, 2025). "Of fact, it has been reported that the anti-tumor effect of MSC may be partly related to the activity of the TIMP-1 and TIMP-2." (PMID 38664697, 2024). "Additionally, KLF4 inhibits the migration and invasion of tumor cells by suppressing biological enzymes like TIMP-1 and TIMP-2." (PMID 39000273, 2024). "Determining TIMP1 and TIMP2 mRNA levels confirmed that the correlation with tumor grade is negative." (PMID 38474106, 2024). "Additionally, increased TIMP-2 levels have been suggested as a marker of low metastatic potential in MTC, since it was observed to be inversely correlated to calcitonin and tumor stage." (PMID 36156766, 2023). "Propofol decreased hypoxia inducible factor 1α (HIF1α), interleukin 1β (IL1β), and hepatocyte growth factor (HGF) gene expressions and increased tissue inhibitor of metalloproteinases 2 (TIMP-2) gene and protein expression in comparison to sevoflurane in the tumour tissue." (PMID 35953652, 2023). "In premenopausal patients (n = 11), six genes were statistically significantly down-regulated in tumour tissue compared to tumour-adjacent tissue: TIMP3 (13.1-fold), ENPP2 (11.4-fold), FGF2 (7.6-fold), CXCL12 (7.5-fold), TIMP2 (5.2-fold), and PDGFRB (4.9-fold change)." (PMID 37509322, 2023).
tumor (continued). "The ONCOS-210 and ONCOS-212 oncolytic adenoviruses, which express both PADI1 and TIMP2, and the combination (ONCOS-207 + ONCOS-209) significantly inhibited A2058 tumor growth in the nude mouse model compared with the vehicle-treated group and the single-transgene vectors ONCOS-207 and ONCOS-209." (PMID 36816748, 2023). "In pancreatic cancer, SHh indirectly promotes tumor angiogenesis by inducing Ptch1 and Gli1, thereby inhibiting two enriched stroma-derived antiangiogenic factors (THBS2 and TIMP2), and directly promotes tumor angiogenesis by activating small GTPases of the RHO family in the presence of VEGF." (PMID 36517618, 2022). "The results showed that TIMP2 was much lower in tumor tissues than in paired adjacent normal tissues (p < 0.001; n = 23), which was consistent with the results extracted from CPTAC protein database." (PMID 35443741, 2022). "Western blot analysis further showed that MG treatment downregulated the expression of vimentin, MMP-2 and MMP-9, and upregulated the expression of E-cadherin and TIMP-2, indicating that MG significantly inhibited the EMT and ECM degradation, and prevented tumor metastasis." (PMID 35770085, 2022). "Moreover, the authors found that the MMP-2/TIMP-2 ratio is higher in CRC tissue compared with healthy tissue, and decreases with tumor stage, depth of invasion and lymph node metastasis." (PMID 34071492, 2021). "Based on our results, we can suggest greater utility of serum TIMP-1 compared with MMP-9, MMP-2, and TIMP-2 in the diagnosis of CRC, particularly in the assessment of the tumor stage, survival of cancer patients, resectability of the tumor, and in the differentiation between CA and CRC." (PMID 34071492, 2021). "Overexpression of TIMP-1, TIMP-2, and TIMP-3 reduces tumor growth." (PMID 35201460, 2021). "However, functional investigations have demonstrated that TIMP-2 administration reduced the tumor growth, and enforced TIMP-2 expression reduced the tumor invasion." (PMID 33808504, 2021). "It was found a low expression of MT1-MMP tissue inhibitor TIMP-2, which makes the main contribution to the destructive (invasive) potential of the tumor; expression of MT1-MMP was detected in morphologically normal tissue adjacent to the tumor." (PMID 34830452, 2021). "The lncRNA lncRNA-LET (lncRNA-low expression in tumor) acts as a competing endogenous RNA of the oncomiR miR-373-3p, and blocks miR-373-3p-mediated Dickkopf-1 (DKK1) and tissue inhibitor of metalloproteinase-2 (TIMP2) down-regulation." (PMID 33593347, 2021). "Among all of the tumor samples, MMP-2 was expressed in 66% of them and TIMP-2 in 53%." (PMID 32751899, 2020). "In particular, TIMP2 and MMP2 also function in tumor invasion." (PMID 33203436, 2020). "It is possible that high expression of TIMP-2 in tumours is a pre-requisite for constitutive activation of STAT3 in many cancers or vice versa, constitutive activation of STAT3 may sustain enhanced TIMP-2 expression in certain cancers." (PMID 33023532, 2020). "Expression of matrix metalloproteases 2, 9 and 14 (MMP-2, MMP-9, MMP-14), tissue inhibitors of metalloprotease 1 and 2 (TIMP-1, TIMP-2) and vascular endothelial growth factor A (VEGF-A) is involved in tumor invasion and metastasis via extracellular matrix degradation and angiogenesis." (PMID 32669083, 2020). "Similarly, except for its MMP-inhibitory activity, TIMP-2 can inhibit cancer progression independently of MMP-mediated mechanisms, probably by modulating tumor cells and the tumor microenvironment." (PMID 33321708, 2020). "Our previous studies performed on GC, CC and EC patients have also revealed that the serum levels of MMP-2 and TIMP-2 did not significantly correlated with clinico-pathological parameters of tumor." (PMID 30719232, 2019). "This highlights a level of redundancy between TIMP2 and TIMP3 activities and raises the intriguing idea that combinatorial administration of TIMP2 and TIMP3 to tumors may augment previous anti-tumor findings observed with TIMP2." (PMID 31882975, 2019).
tumor (continued). "Moreover, in the differentiation between PC and CP patients, the AUC for TIMP-2 (0.6532, p = 0.004) was higher than for MMP-2 (0.5378, p = 0.47), but lower than AUC for classical tumor marker (CA 19-9 – 0.7765, p < 0.001; CEA – 0.7193, p < 0.001)." (PMID 30719232, 2019). "We found that TIMP-2 expression was downregulated in tumor tissues compared with the paired adjacent non-tumor tissues (P < 0.001)." (PMID 31293204, 2019). "In the evolving TME with both tumor and stromal cells (fibroblast, inflammatory and endothelial cells) that express increasing levels of active MMPs, first the MMP-independent functions and eventually the MMP-inhibitory activity of TIMP2 is overwhelmed." (PMID 31882975, 2019). "The expression of TIMP-2 was similar, and no statistical significance was noticed between tumor and stroma while the expression level was higher in tumor tissue." (PMID 31223594, 2019). "Similar results were found in our previous studies concerning other gastrointestinal neoplasms, where the serum MMP-2 and TIMP-2 levels were not correlated with tumor stage." (PMID 30719232, 2019). "Bioinformatic analysis of the identified gene list highlights a core of matrix and matrix-associated genes that are of interest as potential modulators of TIMP2 function, thus ECM structure, identifying potential tumor microenvironment biomarkers and/or therapeutic targets for further study." (PMID 31882975, 2019). "Similarly, miR221/222 have an oncogenic role (by targeting TIMP2 and semaphorin 3B) and the LncRNA GAS5 (Growth arrest-specific 5), which targets miR-222, functions as a tumor suppressor." (PMID 29261132, 2017). "Ursolic acids could inhibit the migration and invasion of tumor stem cells through downregulating MMP-2 and upregulating TIMP-2, while EGCG could inhibit STAT3 signaling pathway." (PMID 28969057, 2017). "Our findings showed DAPK and TIMP2 to be methylated in most samples from both tumor tissues and adjacent non-neoplastic margins; thus presenting distinct methylation patterns." (PMID 26363785, 2015). "It is known that when endothelial cells are subjected to hypoxic conditions (low PO2) such as inside of a tumor mass, MMP2 expression is elevated, and its specific endogenous inhibitor TIMP-2 and the hypoxic conditions enhance MMP2-dependent endothelial cell migration." (PMID 25887757, 2015). "We found that GBC-SD cells in control group passed more of the Transwell membrane and had more invasive capability than TIMP-2 or NCTD group in vitro; the number of passing membrane cells i.e, invated tumor cells in TIMP-2 or NCTD group markedly decreased (P < 0.001)." (PMID 24628713, 2014). "Both the epithelial and the stromal cells being the source of MMP-2 and TIMP-2 in ECM degradation and subsequent cellular motility may facilitate tumor invasion and metastasis." (PMID 24591757, 2014). "With respect to expression of both MMP-9 and TIMP-2, MG63 exhibited the most pronounced upregulation response to an in vitro microenvironment that most resembled in vivo tumor growth conditions; both of these biomarkers are consistently expressed in OS biopsy samples." (PMID 23914349, 2013). "The survival rate in the 5 years following tumor resection was estimated to be 95, 85, 20 and 0% for patients with -, +, ++ and +++ MMP-7 expression, respectively, and 50, 80, 93 and 100% for patients with -, +, ++ and +++ TIMP-2 expression, respectively." (PMID 23408109, 2013). "In addition to the detection method of tumor growth, another explanation is the number of HSA/TIMP-2 administrations." (PMID 22545131, 2012). "Moreover, repression of the MMP inhibitor TIMP2 and serine protease inhibitor SLPI can enhance tumor invasion and has been reported in several cancers." (PMID 23024765, 2012). "Surprisingly, epithelial MMP-9 and stromal TIMP-2 expressions correlated with poor survival, while tumor type, grade and stage did not." (PMID 22200690, 2012).
tumor (continued). "In HSA/TIMP-2-treated tumor tissues, MMP-2 expression was profoundly decreased without a change in MT1-MMP expression of PECAM-1-positive cells." (PMID 22545131, 2012). "In the tumor microenvironment, an imbalance may arise from an increase in MMP expression/activity and a decrease in the expression of the MT-MMP inhibitors, TIMP-2 or TIMP-3." (PMID 21349159, 2011). "The schedule of the concurrent administration group could inhibit the tumor growth better, and it down-regulated MMP-2 expression through TIMP-2 and EMMPRIN, and thus slow down the tumor growth superiorly to another schedule of treatment." (PMID 20681443, 2010). "Combination therapy with SYY plus IFN-α, by regulating the MMP2/TIMP2 ratio and VEGF expression, could be an effective therapeutic strategy to reverse the tumor-enhancing effect derived from hepatectomy." (PMID 20969807, 2010). "Matrix metalloproteinase-8 and TIMP-1 were also significantly increased, whereas tumour TIMP-2 levels were found not to be enhanced." (PMID 16538217, 2006). "Plasma concentrations of MMPs, TIMPs, and MTC1 except for TIMP2 were higher in the group of metastasized tumours compared to the patients of non-metastasized TCC." (PMID 16901349, 2006). "Tissue inhibitor of metalloprotease 2 (TIMP-2), an endogenous inhibitor of MMP-2, has been shown to inhibit invasion and metastasis and overexpression of TIMP-2 inhibited growth and reduced invasive potential in tumor cells." (PMID 15918904, 2005). "Our research focused on a set of genes involved in inflammation and tumor progression such as interleukin 8 (IL-8), intercellular adhesion molecule 1 (ICAM-1), monocyte chemoattractant protein-1 (MCP-1), metallopeptidase inhibitor 2 (TIMP-2) and the transcription factor NF-kB." (PMID 41596621, 2026). "However, TIMP-2 has a different mechanism of action from MMP; some of its functions have been shown to function independently from MMPs, and it can inhibit tumor growth and angiogenesis and may reduce the migration and invasiveness of cancer cells." (PMID 37176095, 2023). "However, the prognosis of TIMP2 in different cancers and its correlation with tumor microenvironment and immunity have not been clarified." (PMID 36304987, 2022). "However, distinct variations in functional outcomes related to in vitro chemosensitivity, and in vivo tumour burden and metastatic dissemination in peritoneal organs existed between CRISPR/Cas9 edited gRNA2 and gRNA1 cells which had different levels of TIMP-2 suppression." (PMID 36585738, 2022). "In this context, we may also consider that the anti-tumor acivity of AD-MSCs can be to a certain extent clarified by their high amounts of pro-angiogenic molecules and MMPs which secrete, whereas hUCESCs segregate large amounts of TIMP-1 and TIMP-2." (PMID 34112253, 2021). "MMP2 (log2 fold change = 7.47), MMP9 (log2 fold change = 3.63), and TIMP2 (log2 fold change = 2.66) displayed increased expression in the TME, while MMP13 (log2 fold change = −4.41) and TIMP1 (log2 fold change = −2.26) displayed increased expression in the HCC tumor." (PMID 33995488, 2021). "TIMP-2 expression was low or absent in both tumor and normal tissues." (PMID 34830452, 2021). "In addition to MMP-2 and TIMP-2, MMP-7 is also relevant for tumor pathogenesis." (PMID 32751899, 2020). "Additionally, in statistical analyses, MMP-2 in tumor-stroma (T-S), MMP-9 (T-S), TIMP-1 (T-S), and TIMP-2 (T-S) variables were introduced in order to determine the differences in the expression of metalloproteinases and their inhibitors between the tumor and stroma." (PMID 31223594, 2019). "Tissue inhibitor of metalloproteinase-2 (TIMP-2) is a unique inhibitor among the TIMP family members, because it not only correlates with matrix remodeling and angiogenesis suppressing but also involves in the process of tumor growth, inflammation, and other diseases." (PMID 31293204, 2019).
tumor (continued). "In 4T1 tumor section specimens, we found that 150 mg/kg decreased MMP-9 to 38.54% compared with 75% in the control group, increased TIMP-1 to 76.04% compared with 31.25% in the control group, and increased TIMP-2 to 66.15% compared with 33.33% in the control group, respectively." (PMID 28088791, 2017). "The protein TIMP-2, initially described as an inhibitor and regulator of the activity of matrix metalloproteinase-2 (MMP-2), has recently been proven to stimulate cell growth and angiogenesis, as well as inhibit apoptosis, hence contributing to tumour aggressiveness." (PMID 23289974, 2013). "We have recently shown that TIMP-2-mediated inhibition of tumor growth is independent of matrix metalloproteinase-mediated mechanisms, and is a consequence of modulating both the tumor cells and the tumor microenvironment." (PMID 23371049, 2013). "Therefore, MMP-7 and TIMP-2 may be useful molecular markers for evaluating prognosis in CCRCC patients and MMP-7 may be a new target for the prevention of tumor development and improvement of survival rate." (PMID 23408109, 2013). "TIMP-2 functions as an endogenous inhibitor of both angiogenesis and tumor growth, effects that may be dependent or independent of MMP inhibition." (PMID 23371049, 2013). "Quantitative analysis indicated that the level of MT1-MMP in PECAM-1-positive blood vessels did not significantly differ between control and HSA/TIMP-2-treated tumors (P = 0.918), which was confirmed by western blotting of tumor lysates from the HSA/TIMP-2-treated group (P = 0.096)." (PMID 22545131, 2012). "On the other hand, TIMP-2 score values at the tumor center correlated inversely with CD3 (r = −0.23, p = 0.021) or with CD20 (r = −0.21, p = 0.036) count in the invasive front, but correlated directly with CD68/(CD3+CD20) ratio in this same tumor location (r = 0.24, p = 0.014)." (PMID 23300781, 2012). "Low TIMP2 expression levels in BC vs. benign and control tissues have been previously reported, indicating that TIMP2 down-regulation with abundant MMP activation, represents a mechanism of tumor invasion and could be used as a novel prognostic indicator in BC." (PMID 21483670, 2011). "Immunoreactivity to VEGF-A, bFGF, TGF-β, MCP-1, TSP-1, TIMP-1, TIMP-2, and endostatin was observed mainly in HCC cells and hepatocytes, showing a predominant cytoplasmic staining with positive liver cells distributed throughout the tumor tissue and the surrounding liver." (PMID 20716344, 2010). "The immunoreactivity of VEGFA, bFGF, TGF-β, MCP-1, TSP-1, TIMP-1, TIMP-2, and endostatin was observed mainly in the tumor and non-tumor hepatic cells, showing a predominant cytoplasmic staining, with the positive liver cells distributed in both the tumor tissue and surrounding liver." (PMID 21152281, 2010). "In this study, practically none of the endothelial or tumor cells expressed TIMP-1 or TIMP-2." (PMID 18954439, 2008). "As a result, tumours with a high TIMP-2/MMP ratio may be more sensitive to chemotherapy due to their docile non-aggressive nature in contrast to tumours with a low TIMP-2/MMP ratio which, because of their inherent proteolytic nature, may be more resistant to chemotherapy." (PMID 36585738, 2022). "Even though these studies used immunohistochemistry of tumor sections, none used a marker to identify tumor areas, but relied on automated analytical systems that provided the overall expression of TIMP-2 in tumors, which may not correspond to positive neoplastic cells." (PMID 35047406, 2021). "In addition, both CM presented a remarkable quantity of different proteins that have been associated with antioxidant and/or anti-inflammatory effects and may thus mediate the viability of non-tumor cells, such as AIFM1, ANXA5, CD9, CDH13, GDF15, GSR and TIMP2." (PMID 34884877, 2021).